METTL3 (methyltransferase 3, N6-adenosine-methyltransferase complex catalytic subunit)
Diseases named in the same sentence as METTL3 in open-access papers (continued):
Sharing a sentence is not in itself a finding about the gene and the disease.
tumor (continued). "Since METTL3-mediated m6A modification could enhance PD-L1 mRNA stability through the METTL3-IGF2BP3 axis, tumor immune cell infiltrations and CD8+ T cell functions were enhanced forcefully when METTL3 or IGF2BP3 is inhibited." (PMID 36035182, 2022). "Moreover, the depletion of methyltransferases METTL3 and METTL14 in tumor cells is found to prominently induce the activation of the IFN-γ-STAT1-IRF1 signaling axis through the stabilization of the STAT1 and IRF1 mRNA via YTHDF2." (PMID 35693795, 2022). "Moreover, METTL3/IGF2BP3 inhibition reduces the stabilization of PD-L1 mRNA, thus enhancing anti-tumor immunity through T-cell activation, exhaustion and infiltration." (PMID 36428700, 2022). "Taken together, these results indicate that METTL3 induces STEAP2 translation in an m6A-dependent manner, subsequently leading to inactivation of the Hedgehog signaling pathway and EMT, and restrains aggressive tumor phenotypes." (PMID 35436987, 2022). "We investigated the impact of METTL3 and ACIN1 on tumor growth in vivo." (PMID 35255776, 2022). "However, another study found that METTL3 cooperates with YTHDF2 to regulate downstream c-Rel and RelA, participates in the inactivation of the NF-κB pathway, and plays a key tumor-suppressing role in papillary thyroid cancer." (PMID 35945641, 2022). "In addition, a few studies have suggested that certain writers (METTL3, METTL14, and ZC3H13) exert a tumor-suppressing effect." (PMID 35945641, 2022). "Indeed, METTL3 is significantly overexpressed in DLBCL tissues and cell lines, ultimately promoting the proliferation of tumor cells." (PMID 35053496, 2022). "The methyl transferase METTL3 is up-regulated in brain tumors leading to the methylation of CPEB2 mRNA, which in turn stabilizes the splicing factor SRSF5 mRNA, leading to the incorporation of exon 7 in ETS-1 in models of the Blood–Tumor Barrier." (PMID 36064747, 2022). "In addition, IHC staining showed that METTL3 depletion increased APC expression with corresponding decreased expression of β-catenin, cyclin D1, c-Myc and PKM2 in tumour tissues." (PMID 34155197, 2021). "Notably, we observed that m6A “writers” METTL3 and METTL14 mRNA levels were respectively decreased by ~75% and ~49% in tumor-infiltrating NK cells of HCC patients." (PMID 34535671, 2021). "METTL3 depletion in macrophages contributed to the formation of an immunosuppressive microenvironment with increased Treg infiltration and reduced Th1 cells and IFN-γ+CD8+ cells, and subsequently facilitated tumor growth and metastasis." (PMID 34526985, 2021). "Consistent with the tumour-promoting effect of METTL3 overexpression, overexpression of WT, but not the inactive mutant, METTL3 increased the amount of lactate in tumour tissue." (PMID 34155197, 2021). "METTL3/METTL14-catalyzed m6A methylation and NSUN2-induced m5C methylation can jointly enhance the expression of p21 mRNA in response to oxidative stress-triggered cellular senescence in tumor cells." (PMID 33754077, 2021). "Nevertheless, using the TCGA and CPTAC tumor dataset, we did not observe substantial genetic alterations or upregulations of METTL3 and METTL14 in cancer." (PMID 34285249, 2021). "METTL3 is also upregulated in breast cancer, where it increases methylation and stability of HBXIP mRNA, which induces cell proliferation and survival of tumour cells via inhibiting the tumour suppressor let-7 g." (PMID 33461542, 2021). "Therefore, although METTL3 has been reported to exert a cancer-promoting function in NSCLC, it is crucial to elucidate the unexpected tumor-suppressive role of m6A modification initiated by METTL3 in LUAD." (PMID 33676554, 2021). "In BC cells, we found that silencing METTL3 could inhibit EMT and tumor cell invasion by suppressing MALAT1." (PMID 34419065, 2021).
tumor (continued). "Collectively, we identified the pivotal role of METTL3‐catalyzed m6A modification in CRC tumorigenesis, wherein it facilitates CRC tumor growth and metastasis through suppressing YPEL5 expression in an m6A‐YTHDF2‐dependent manner, suggesting a promising strategy for the diagnosis and therapy of CRC." (PMID 33411363, 2021). "We chose some regulators for RT-qPCR validation, and the qPCR results revealed that METTL3, METTL14, and FTO had consistently low expression in 33 paired samples with TCGA data, while YTHDF1 and YTHDF3 showed increased expression in tumor samples compared to adjacent tissues." (PMID 34804948, 2021). "In addition, METTL3 strengthened the stability of MYC in a METTL3-m6A-YTHDF1-mediated manner, thereby stimulating tumor progression." (PMID 33879256, 2021). "Meanwhile, METTL3, and YTHDC2 were suppressed in tumor samples." (PMID 33748145, 2021). "METTL3-mediated deposition of m6A can accelerate SOCS recognition and promote IL2-STAT5 signaling pathway activation, which can maintain the immunosuppressive function of Treg and inhibit tumor progression." (PMID 34136491, 2021). "Decreased m6A level by knockdown of the expression of METTL3 and/or METTL14 or overexpression of the eraser FTO can significantly accelerate tumorigenesis, specifically promoting the growth of human GSCs, as well as their self-renewal and tumor progression." (PMID 34381710, 2021). "Interestingly, METTL3 also upregulated HBXIP expression following the marked increase of overall m6A methylation, favoring the positive feedback loop HBXIP/let-7g/METTL3/HBXIP, which strongly promoted tumor cell growth and metastasis." (PMID 34722298, 2021). "In addition, knockdown of the m6A writers METTL3 and METTL14 significantly increases GSC-initiated tumor progression in vivo." (PMID 34113622, 2021). "Our findings initially unveiled the role of METTL3 in TNBC, and theoretically, it suggests that METTL3 may be a critical tumor suppressor of TNBC." (PMID 35004298, 2021). "To confirm the TME-mediated decreased METTL3 protein expression in NK cells, we cocultured NK cells with MC38 tumor cells and consistently found that MC38 cells could decrease METTL3 protein expression in NK cells." (PMID 34535671, 2021). "Consistently, overexpression of METTL3 but not methyltransferase activity mutant METTL3 can promote cell migration, spheroid formation in cell line and tumor growth in xenograft model." (PMID 34631715, 2021). "Tumor suppressors NKX3.1 and LHPP were the precise targets of METTL3 and YTHDF2." (PMID 34899855, 2021). "Overall, METTL3‐mediated m6A modification contributes to the upregulation of PCAT6 in an IGF2BP2‐dependent manner and the PCAT6/IGF2BP2/IGF1R complex further stabilizes IGF1R mRNA to activate downstream pathways, which promotes BM and tumor growth in PCa." (PMID 34185427, 2021). "However, it seems contradictory for METTL3, METTL14, and WTAP, the three components of the methyltransferase complex, to exhibit different effects on tumor cells." (PMID 33314339, 2021). "Moreover, the interaction between METTL3 and lncRNA LINC00470 promoted tumor growth by impairing the stability of PTEN mRNA." (PMID 33879256, 2021). "The authors showed that tumor xenografts with METTL3 knockdown cells showed significantly smaller tumor sizes and volumes compared with non-targeted shRNA control cells in nude mice." (PMID 34298617, 2021). "Furthermore, data generated from m6A-squencing portray a regulatory network of Mettl3-modulated TEK/PI3K/VEGF axis, which propels the angiogenesis surrounding tumor cells." (PMID 33681207, 2021). "METTL3-and METTL14-induced dysregulated m6A modification could account for the aberrant expression of LNCAROD and lead to the malignant behaviour of tumour cells." (PMID 35004679, 2021). "In conclusion, the m6A methyltransferases METTL3, METTL14, WTAP, KIAA1429, and METTL4 are dysregulated in ccRCC and might act as tumor suppressor genes." (PMID 35474700, 2021).
tumor (continued). "In solid tumors, METTL3-mediated m6A modification of MYC mRNA regulates the stability of the corresponding RNA in urothelial carcinoma, prostate carcinoma (PC) and oral squamous cell carcinoma (OSCC), thereby enhancing tumor development." (PMID 34315512, 2021). "And the results indicated that knock-down of NKX3–1 and LHPP could significantly induced the tumor growth, but knock down of YTHDF2 or METTL3 partially rescued the mice tumor growth induced by knock down of LHPP and NKX3–1." (PMID 33121495, 2020). "Only recently the expression profiles of 13 m6A-related genes in 317 OSCC and 32 normal samples from The Cancer Genome Atlas (TCGA) database had been analyzed and found a significantly higher expression of eight genes, including METTL3 and METTL14, in tumor tissues." (PMID 32957697, 2020). "Other mRNA transcripts, including AFF4, IKBKB, RELA, and MYC, were revealed to be targets of METTL3 and mediated the role of METTL3 in promoting cell proliferation, invasion, and survival, whereas SETD7 and KLF4 tumor suppressors were negatively regulated by METTL3 in a YTHDF2-dependent manner." (PMID 32854717, 2020). "In addition, it has also been shown that overexpression of METTL3 contributes to a poor prognosis in CRC and HCC and correlates positively with tumor metastasis." (PMID 32429972, 2020). "Compared with the control (shNC), the tumours in the METTL3 knockdown groups (shRNA1 and shRNA2) did not grow or were gradually absorbed under the skin." (PMID 33090698, 2020). "Furthermore, overexpression of METTL3 dramatically increased DLD1 tumor growth and tumor weight in xenograft mouse models." (PMID 32245489, 2020). "Although both of METTL3 and METTL14 could act as m6A “writer”, METTL3 might promote the progression of CRC, while METTL14 functions as a tumor suppressor in CRC." (PMID 33015074, 2020). "We further found that the direct CD33+CD11b+HLA-DR− MDSC induction and tumour-derived MDSC induction in vitro were decreased in the absence of METTL3." (PMID 33059689, 2020). "METTL3 was shown to promote the proliferation and migration of hepatocellular carcinoma via the YTHDF2-dependent pathway and its knockdown could inhibit tumor progression." (PMID 33240891, 2020). "Consistent with in vitro experiments, in vivo tumours derived from TCam‐2/CDDP cells with METTL3 overexpression grew more rapidly than negative control under CDDP treatment and the growth was inhibited by IGF2BP1 inhibition." (PMID 32857912, 2020). "Collectively, it can be certain that METTL3 plays important role in CRC progression, but whether it serves an oncogene or a tumour suppressor gene is controversial." (PMID 33029866, 2020). "Moreover, METTL3 silencing also reverses RasV12-mediated malignant transformation of mouse immortalized astrocytes and suppresses GBM tumor growth in vitro and in vivo." (PMID 32244981, 2020). "Recent findings showed that METTL3 expression was higher in CRC tissues than in normal tissues and that this feature indicated poor prognosis; upregulation of METTL3 promoted CRC tumor growth by stabilizing SRY-box 2 (SOX2) and cyclin E1 (CCNE1) mRNA in an m6A-dependent manner." (PMID 32429972, 2020). "In contrast, both m6A methyltransferases (METTL3 and METTL14) and m6A demethylases (FTO) act as tumour suppressor genes in renal cell carcinoma, indicating that the recruited m6A‐binding protein and potential downstream target play important roles in tumour development." (PMID 32808488, 2020). "Our results indicate that the high expression of METTL3 is related to the high SUVmax in ESCA, and that 18F-FDG PET may help determine the therapeutic strategy for ESCA patients by predicting tumor response to METTL3-targeted therapies." (PMID 32626532, 2020). "As oncogenes of AML, METTL3, METTL14, WTAP, FTO, YTHDF2, and IGF2BP1 participate in tumor processes through a variety of pathways, including the promotion of the growth of cancer cells and inhibition of apoptosis." (PMID 33519919, 2020).
tumor (continued). "However, recently METTL3 and METTL14 were reported to proliferation and migration of suppress CRC through regulating the p38/ERK pathway and tumor suppressor miR-375, respectively." (PMID 32513173, 2020). "High levels of METTL3 expression have been shown to significantly upregulate m6A methylation in the coding sequences of SOX2 mRNA, a well-known CrC marker that is involved in maintaining the properties of tumor-initiating cells." (PMID 32404927, 2020). "Consistently, METTL3 serves as an oncogene, but METTL14 is a tumor suppressor in HCC." (PMID 33159022, 2020). "Furthermore, the expression of IGF2BP1, METTL3 and METTL14 is strongly correlated with E2F1–3 expression (R = 0.4) across 33 TCGA tumor cohorts." (PMID 32761127, 2020). "A previous study discovered that the “writers” of m6A methylation, METTL3 and METTL14, could play both oncogenic and tumor suppressor roles in numerous cancers, while oncogenic roles have been reported for “erasers” such as FTO and ALKBH5." (PMID 31722709, 2019). "Stable cells with modified METTL3 expression were injected into the tail vein of BABL/c nude mice, and luciferase signals were monitored at different time points to observe the location and growth of tumor xenografts in the lung." (PMID 31607270, 2019). "Remarkably, we detected a significantly more enrichment of NFIC within METTL3 regulatory region in non-tumor pancreatic tissues from smokers than that from nonsmokers." (PMID 31015415, 2019). "Moreover, METTL3 or IGF2BP2 expression positively correlated with the SOX2 downstream genes CCND1, MYC, and POU5F1 in our independent cohort of paired CRC tumor and adjacent normal tissues from SYSUCC." (PMID 31230592, 2019). "c, Tumor incidence showing the tumorigenesis of the indicated serial of cell numbers of METTL3 knockdown and control SW620 cells with or without SOX2 overexpression." (PMID 31230592, 2019). "Methyltransferase-like 3 (METTL3), a predominantly catalytic enzyme in the N6-methyladenosine (m6A) methyltransferase system, is dysregulated and plays a dual role (oncogene or tumor suppressor) in different human cancers." (PMID 31921660, 2019). "To investigate the potential role of METTL3 in tumor progression, we firstly noted that METTL3 was elevated in SW620 cells compared with SW480 cells, a pair of cell lines isolated from abdominal metastatic foci and the primary tumor, respectively, of a single patient." (PMID 31230592, 2019). "Compared to mice grafted with control cells, mice transplanted with PBT003 cells having METTL14 KD or METTL3 and METTL14 double KD developed much bigger tumors, as revealed by a dramatic increase in tumor luciferase activity at week 4, 5, or 6 after GSC transplantation." (PMID 28297667, 2017). "Likewise, when we transplanted PBT726 cells with KD of METTL3 or METTL14 into the brains of NSG mice, we observed a substantial increase in tumor growth compared to that in mice transplanted with control cells." (PMID 28297667, 2017). "METTL3 facilitates MDSC migration through the basic helix‐loop‐helix family member e41 (BHLHE41)–CXC motif chemokine ligand 1 (CXCL1)/CXCR2 axis, which may influence tumor cells’ metastatic potential." (PMID 39802639, 2025). "Moreover, METTL3 can directly bind to the 5’-UTR or 3’-UTR of HK2 and the 3’-UTR of glucose transporter(GLUT1), stabilizing gene expression via IGF2BP2 or IGF2BP3 and activating the glycolysis pathway to modulate tumor cell progression." (PMID 40483535, 2025). "Tumor growth was rescued by overexpressing wild-type METTL3, but not METTL3A155P." (PMID 41321637, 2025). "In brief, METTL3-modificatory m6A regulates the interaction of PANC754 with PSPC1 and H3K4me1 to form ncRNA/RBP/histone repression complex at gene promoter region to mediate the “Don’t eat me” LGALS7 signaling pathway, thereby exerting tumor-suppressing effects against CRC." (PMID 40634299, 2025).
tumor (continued). "RNA modifications can be catalyzed, erased and recognized by methyltransferases such as METTL1, METTL3, METTL16, and accurately regulate the process of methylation, which plays an important role in the proliferation, metastasis, invasion, apoptosis, autophagy, and drug-resistance of tumor cells." (PMID 40443650, 2025). "Furthermore, we established that FOSL1 positively regulates global m6A methyltransferase activity in a PRMT1-dependent manner, influencing the expression and function of key RNA methyltransferase METTL3 and its target transcripts involved in DDR and tumor progression." (PMID 41423530, 2025). "Hence, we speculate that the METTL3/miR-146a-5p/SMAD4 axis could serve to facilitate this switch in OSCC, thereby converting the tumor-suppressive properties of TGF-β signaling into tumor-promotive capabilities." (PMID 40338154, 2025). "We found an unexpected negative correlation between METTL3 mRNA expression levels and tumor purity." (PMID 40177651, 2025). "Similarly, the three writers, METTL3, METTL16, and ZC3H13 have all been shown to influence PTC progression, tumor size, and prognosis, and as the up- or down-regulation of the enzymes is associated with PTC, they may also be useful as biomarkers of disease." (PMID 40243425, 2025). "Therapeutically, targeting m6A regulators—such as through inhibition of METTL3 or FTO—disrupts tumor-intrinsic immune resistance and reshapes extrinsic immunosuppressive networks, thereby enhancing the efficacy of immune checkpoint inhibitors in cold tumor settings." (PMID 41050070, 2025). "For instance, METTL3 is essential for the development and maintenance of myeloid leukemia in both mice and humans, modulates the Wnt/β-catenin-EMT axis in ESCC by stabilizing β-catenin/TCF4 transcriptional complexes to facilitate tumor invasion, and facilitates TGFβ signals to support tumor growth." (PMID 40612868, 2025). "When dissociated from METTL3, METTL14 may be more inclined to stabilize tumor suppressor RNA." (PMID 41256854, 2025). "Mechanistically, Mettl3 stabilizes Pfkfb3 mRNA through N6-methyladenosine (m6A) modification and subsequently induces lactate production to upregulate the PD-L1 expression via H3K18 lactylation, thereby promoting both tumor growth and CDDP-induced renal damage." (PMID 40765834, 2025). "Therefore, METTL3 collaborates with YTHDF1 to promote tumor progression and attenuate the efficacy of tumor therapy by targeting the SPRED2/ERK/NF-kB-STAT3 signaling pathway, highlighting the clinical possibilities of using METTL3 as a target in tumor immunotherapy." (PMID 39416774, 2024). "High levels of miR-4443 inhibit cisplatin induced tumor death by reducing the expression level of METTL3 and increasing the level of FSP1, suggesting that miR-4443 plays an important role in cisplatin resistance in NSCLC through the METTL3/FSP1 mediated ferroptosis." (PMID 38550378, 2024). "In colorectal cancer (CRC), METTL3 upregulates plasminogen activator urokinase (PLAU) mRNA in a m6A-dependent manner and participates in the mitogen-activated protein kinase (MAPK)/extracellular signal-regulated kinase (ERK) pathway to promote tumor angiogenesis and metastasis." (PMID 39295872, 2024). "Similarly, M2-TAMs are greatly increased in the tumor tissues of patients with immunoresistant LUAD and enhance the expression of METTL3 and total m6A RNA level, while interfering with METTL3 could significantly reverse immunoresistance." (PMID 38322265, 2024). "Moreover, in vivo, it lessens the tumor volume and halts DNMT1 and METTL3 expression in BC mice." (PMID 38961497, 2024). "In our study, we found that the overexpression of METTL3 enhanced the chemosensitivity of TC cells in both PTC and ATC cells, suggesting that METTL3 might be an important tumour suppressor gene and provide novel approaches for potential therapeutics." (PMID 38993572, 2024).